COL1A1 (collagen type I alpha 1 chain)
Diseases named in the same sentence as COL1A1 in open-access papers (continued):
Sharing a sentence is not in itself a finding about the gene and the disease.
ankylosing spondylitis (1 paper, 2023). An autoimmune chronic inflammatory disorder characterized by inflammation in the vertebral joints of the spine and sacroiliac joints. "Moreover, a regulatory role for miR-17-5p in ectopic bone formation in ligaments has been described in patients of ankylosing spondylitis, wherein it targets and suppresses the ankylosis protein homolog (ANKH) and enhances the expression of COL1A1." (PMID 37239902, 2023).
Aortic dissection (1 paper, 2019). Aortic dissection refers to a tear in the intimal layer of the aorta causing a separation between the intima and the medial layers of the aorta. "VUS of ACTA2 emerged as significantly associated with aortic dissection while COL1A1 and COL1A2 VUS significantly influenced hyperlaxity." (PMID 31536524, 2019).
aortic stenosis (1 paper, 2018). Aortic valve stenosis is a aortic valve disease caused by the incomplete opening of the aortic valve. "An alteration in the COL3:COL1A1 ratio has been observed in a number of fibrotic diseases, including aortic stenosis." (PMID 31069326, 2018).
aortic valve calcification disease (1 paper, 2024). "Previous studies have found that THBS2, COL1A1, and LUM are closely related to aortic valve calcification disease." (PMID 39749331, 2024).
arachnodactyly (1 paper, 2019). "In particular, aortic ectasia resulted significantly influenced by FBN1 rare pathogenic variants and by FBN1, COL1A1 and COL3A1 VUS, arachnodactyly resulted influenced by FBN1 rare pathogenic and VUS rare variant; MYH11 pathogenic variants and FBN1 VUS resulted associated with ectopia lentis." (PMID 31536524, 2019).
aristolochic acid nephropathy (1 paper, 2025). "Similarly, the aristolochic acid nephropathy model, which caused elevated urea levels and Col1a1 and Fibronectin1 mRNA expression at 4 weeks after injection, did not induce AS-Umod mRNA expression." (PMID 40198127, 2025).
B-cell lymphoma (1 paper, 2020). "Further analyses revealed that alteration of the expression of signature genes by ColXV was associated with B-cell lymphoma family and ECM remodeling, especially Bcl-2, Col1a1, Col6a1, MMP-2 and MMP-9." (PMID 32024006, 2020).
Barrett esophagus (1 paper, 2021). Esophageal lesion lined with columnar metaplastic epithelium which is flat or villiform. "Furthermore, COL1A1 expression was closely associated with Barrett’s esophagus (p = 0.003), family history (p = 0.016), histology type (p = 0.048), and reflux history (p = 0.030)." (PMID 34395525, 2021).
benign pancreatic tumors (1 paper, 2025). "In benign pancreatic tumors, the increased proline hydroxylation of COL1A1 could be indicative of a more robust ECM, which may serve as a physical barrier to tumor cell dissemination." (PMID 40216311, 2025).
bone metabolism disorders (1 paper, 2008). "Highly connected sub-networks of proteins associated with CKD, CVDs or bone metabolism disorders were detected involving proteins like collagens (COL1A1, COL1A2), fibronectin, transforming growth factor-β1, or components of fibrinogen (FG-α, FG-β, FG-γ)." (PMID 18266955, 2008).
bone tumor (1 paper, 2022). "Unexpectedly, the Col1a1-Krm2 transgene did not affect spreading and metastatic outgrowth of MDA-MB-231-SCP2 cells, suggesting that bone tumor interactions are more relevant at later stages of metastatic progression." (PMID 35158823, 2022).
Bowen’s disease (1 paper, 2022). "We found the proteins expressed levels of COL3A1 and COL1A1 were significant decreased in CSCC relative to Bowen disease according to Western blot results." (PMID 36085041, 2022). "And next, among 20 proteins, 8 proteins (TNC, FSCN1, SERPINB1, ACTN1, RAB31, COL3A1, COL1A1 and CD36) expressed levels showed significant differences between CSCC and Bowen disease." (PMID 36085041, 2022). "Besides, the proteins of TNC, FSCN1, SERPINB1, ACTN1 and RAB31 in CSCC were significantly up-regulated, while COL3A1, COL1A1 and CD36 were significantly down-regulated relative to Bowen disease in proteomics results." (PMID 36085041, 2022).
cataract (1 paper, 2018). Partial or complete opacity of the crystalline lens of one or both eyes that decreases visual acuity and eventually results in blindness. "Furthermore, the analysis of TGF-β-responsive genes by RT-qPCR showed increased expression of collagen (COL1A1), fibronectin (FN1), Snail, matrix metalloproteinase 2 (MMP2), and matrix metalloproteinase 9 (MMP9) in the cataracts of transgenic mice as compared to nontransgenic lens samples." (PMID 29888254, 2018).
cholangitis (1 paper, 2021). An acute or chronic inflammatory process affecting the biliary tract. "Therefore, we investigated whether this pathway is involved in progressive fibrosis after cholangitis by analyzing the expression of IL33, IL13, TGFB1, and COL1A1." (PMID 34858903, 2021).
Cholestatic liver disease (1 paper, 2013). "This is supported in other non-granulatomous liver models; for example, in rodent models of cholestatic liver disease increased expression of CCL2 is observed three days after bile duct ligation, with CCL2 expression increasing prior to both αSMA and Col1A1." (PMID 23840855, 2013).
Chorangioma (1 paper, 2026). "Chorangioma-affected tissue harbored pathogenic COL1A1, FBXO11, and TRIM71 somatic mutations, with elevated Leptin expression and oxidative stress signatures." (PMID 41634840, 2026).
chronic thyroiditis (1 paper, 2012). "It is to be emphasized that high expression levels of TGFB1 and of COL1A1 genes in chronic thyroiditis and its correlation with thyroid fibrosis has previously been observed." (PMID 22397327, 2012).
colorectal adenoma (1 paper, 2021). An adenoma that arises from the colon or rectum. "In summary, this study identified a set of differentially expressed genes in CRC, including FcGBP, CLCA1, ADH1C, COL1A1, ZG16, which could be strong candidates to be used as biomarkers of colorectal adenoma-adenocarcinoma progression." (PMID 33648461, 2021).
congestive heart failure (1 paper, 2021). Failure of the heart to pump a sufficient amount of blood to meet the needs of the body tissues, resulting in tissue congestion and edema. "The expression of miR29b decreased and the expression of miR29b ECM target-genes collagen-1A1 (COL1A1), collagen-3A1 (COL3A1) increased significantly in congestive heart failure (CHF) atrial fibroblasts." (PMID 35127848, 2021).
craniosynostosis (1 paper, 2026). Craniosynostosis is defined as the premature fusion of one or more cranial sutures leading to secondary distortion of skull shape resulting in skull deformities with a variable presentation. "Further correlation analysis revealed that circPROSC expression was positively correlated with the expression of osteogenic markers (RUNX2, OPN, and COL1A1), which were significantly elevated in fused cranial suture tissues from craniosynostosis patients." (PMID 41178597, 2026).
diaphragmatic hernia (1 paper, 2025). A congenital or acquired weakness or opening in the diaphragm which allows abdominal contents to protrude into the chest cavity; congenital diaphragmatic hernias are caused when the embryonic diaphragm fails to fuse. "This is the first report of COL1A1 cEDS associated with diaphragmatic hernia in a newborn." (PMID 41356277, 2025).
diastolic heart failure (1 paper, 2025). Heart failure caused by abnormal myocardial relaxation during diastole leading to defective cardiac filling. "An elevated Col1a1/Col3a1 ratio has been implicated in diastolic heart failure in DCM." (PMID 39592912, 2025).
diffuse astrocytoma (1 paper, 2020). A low-grade (WHO grade II) astrocytic neoplasm. "Interestingly, several of these differentially expressed genes identified in our study have also emerged as genes relevant for discriminating distinct subtypes of diffuse astrocytomas in other studies, including the GBM-associated CHI3L1, COL1A1, VEGFA and ANXA genes." (PMID 32647207, 2020).
dislocation (1 paper, 2023). A displacement of a part (especially a bone) from its normal position. "The aim of this study was to assess the coexistence of polymorphisms of the COL1A1 and COL5A1 genes with clinically diagnosed laxity and the occurrence of recurrent patellar dislocation in adolescents." (PMID 38102224, 2023). "Therefore, the aim of this study was to assess the coexistence of polymorphisms of the COL1A1 and COL5A1 genes with clinically diagnosed laxity and the occurrence of recurrent patellar dislocation in adolescents." (PMID 38102224, 2023).
Dupuytren’s disease (1 paper, 2023). "In myofibroblasts from patients with Dupuytren’s disease (DD), a localized fibrotic disorder of the palm, A485 inhibited the profibrotic genes ACTA2 and COL1A1 expression." (PMID 37569677, 2023). "In myofibroblasts from Dupuytren’s disease patients, SGC-CBP30 and I-CBP112 were used to validate CREBBP and EP300 as key regulators of the profibrotic phenotype in myofibroblasts by decreasing the expression of the profibrotic genes ACTA2 and COL1A1." (PMID 37569677, 2023).
Dystrophic epidermolysis bullosa (1 paper, 2022). "Among them, COL1A1 and COL2A2 are linked to “dystrophic epidermolysis bullosa” (DEB) and “localized dystrophic epidermolysis bullosa, pretibial form,” a subtype of DEB, respectively." (PMID 36028515, 2022).
echinococcosis (1 paper, 2022). A parasitic infection caused by tapeworm larvae of Echinococcus. "Mice infected with echinococcosis were also found to show higher COL1A1 and COL3A1 expression levels in the hepatic tissue." (PMID 36034715, 2022).
embryonal carcinoma (1 paper, 2012). A non-seminomatous malignant germ cell tumor characterized by the presence of large germ cells with abundant cytoplasm resembling epithelial cells, geographic necrosis, high mitotic activity, and pseudoglandular and pseudopapillary structures formation. "The promoter region of COL1A1 contains CpG islands, and methylation in this region, as well as in exon 1, depresses COL1A1 gene expression in cultured 3T3 mouse embryo tissue fibroblasts and F9 embryonal carcinoma cells." (PMID 22690110, 2012).
endometritis (1 paper, 2020). An acute or chronic, usually bacterial infectious process affecting the endometrium. "This study confirmed differences in the expression profiles of six biomarkers in LPS-induced bovine endometritis: SLC7A5, COL1A1, AXIN2 (upregulated) and CFD, MGP, CCDC3 (downregulated)." (PMID 32545766, 2020). "The results revealed the dysregulation of the six crucial biomarkers involved in endometritis: SLC7A5, COL1A1, AXIN2 (upregulated); CFD, MGP, CCDC3 (downregulated)." (PMID 32545766, 2020).
Esophageal stricture (1 paper, 2023). A pathological narrowing of the esophagus that is caused by the development of a ring of scar tissue that constricts the esophageal lumen. "Furthermore, TGF-β1, Col1a1, and Acta2 were found to be increased in the tissue with esophageal stricture based on PCR and histological analysis." (PMID 37474710, 2023).
expressive language disorder (1 paper, 2024). "Making providers aware that expressive language disorder/delay is more prevalent in patients with non-COL1A1/1A2 variants can be used to raise awareness and ensure timely intervention." (PMID 39450342, 2024). "There was a significant difference however, in the development of expressive language disorder/delay with higher prevalence in the non-COL1A1/1A2 group." (PMID 39450342, 2024).
Fabry disease (1 paper, 2025). Fabry disease (FD) is a progressive, inherited, multisystemic lysosomal storage disease characterized by specific neurological, cutaneous, renal, cardiovascular, cochleo-vestibular and cerebrovascular manifestations. "Conversely, genes crucial for ECM integrity and maintenance, including ADAMTS5, LOXL1, COL1A1, and COL6A2, were all down-regulated in the patient hURECs, indicating dysregulated ECM dynamics, as previously observed in Fabry disease." (PMID 40673439, 2025).
Fibroadenoma (1 paper, 2022). A benign tumor of the breast characterized by the presence of stromal and epithelial elements. "LC-MALDI TOF/TOF MS analysis, corroborated with iTRAQ data for 22 isoforms of collagen type I alpha-1 chain (COL1A1), indicated an increase in fibrillary collagens in invasive ductal carcinoma (IDC) compared with little change in expression in fibroadenoma (FA) or ductal carcinoma in situ (DCIS)." (PMID 36278695, 2022).
fluorosis (1 paper, 2024). "The Col1a1, Bcl2, Fgfr1, Mmp9, Mmp13, Bmp2, and Bmp7 genes are the key regulatory factors in fluorosis bone metabolism." (PMID 39125380, 2024).
fracture (1 paper, 2017). "Our results revealed that the concentration of IL-6, a key cytokine in the local immune response after bone fracture and in posttraumatic systemic inflammation, was neither locally nor systemically altered in Col1a1-C5aR1 mice." (PMID 28614388, 2017).
gliosarcoma (1 paper, 2019). A rare histological variant of glioblastoma (WHO grade IV) characterized by a biphasic tissue pattern with alternating areas displaying glial and mesenchymal differentiation (WHO). "When compared to GBMs, gliosarcomas show up-regulation of some genes, ranging up to a 6-fold difference on a log2-scale and most top differentiating genes encode collagens (COL1A1, COL6A1, COL6A2, COL6A3, COL1A2, COL3A1)." (PMID 30818875, 2019).
hip fracture (1 paper, 2015). Traumatic or pathological injury to the hip in which the continuity of either the femoral head, femoral neck, intertrochanteric or subtrochanteric regions is broken. "Low bone OC/COL1A1 expression ratio was a predictor of worse trabecular mechanics and of a hip fracture episode." (PMID 26357654, 2015).
HIV-1 infection (1 paper, 2025). The type species of lentivirus and the etiologic agent of acquired immunodeficiency syndrome (AIDS). "In vitro, IL-8 treatment of HSCs elevated α-SMA and COL1A1 expression, implicating IL-8 in fibrosis progression in HIV-1 infection." (PMID 40462917, 2025).
Hodgkins lymphoma (1 paper, 2022). A heterogeneous group of malignant lymphoid neoplasms of B-cell origin characterized histologically by the presence of Hodgkin and Reed-Sternberg (HRS) cells in the vast majority of cases. "In Hodgkin’s lymphoma, COL1A1 overexpression is associated with epigenetic silencing of the RNA demethylase ALKBH3 and reduced survival." (PMID 36873459, 2022).
holoprosencephaly (1 paper, 2019). Holoprosencephaly (HPE) is a complex brain malformation resulting from incomplete cleavage of the prosencephalon, occurring between the 18th and 28th day of gestation, and affecting both the forebrain and face, which results in neurological manifestations and facial anomalies of variable severity. "Next-generation sequencing demonstrated that the family had compound heterozygous mutations in COL1A1 and COL1A2, with no known mutations related to PSIS, pituitary hormone deficiency (PHD), or holoprosencephaly (HPE)." (PMID 30984112, 2019).
Hyperammonemia (1 paper, 2026). An increased concentration of ammonia in the blood. "Chronic liver injury was characterized by progressive fibrosis, elevated expression of COL1A1, and persistent hyperammonemia." (PMID 42186602, 2026).
Hyperinsulinemia (1 paper, 2023). An increased concentration of insulin in the blood. "Under hyperglycemic conditions, hyperinsulinemia slightly upregulated CDH1 (FCHG, ins = 1.23) and COL1A1 expression (FCHG, ins = 0.75) compared to the respective untreated hyperglycemic controls, whereas MMP9 levels (FCHG, ins = 0.56) were downregulated." (PMID 37313172, 2023).
IgA nephropathy (1 paper, 2026). "PALLD was also correlated with COL1A1 in human FSGS and IgA nephropathy samples." (PMID 41131992, 2026).
influenza (1 paper, 2025). An acute viral infection of the respiratory tract, occurring in isolated cases, in epidemics, or in pandemics; it is caused by serologically different strains of viruses (influenzaviruses) designated A, B, and C, has a 3-day incubation period, and usually lasts for 3 to 10 days. "The highest density of versican expression observed in untreated and influenza-infected mice was in mesenchymal cells, identified by Col1a1 and Acta2 expression." (PMID 40766376, 2025).
Intellectual disability (1 paper, 2020). "Published reports of intellectual disability in patients with deletion of COL1A1 and adjacent genes, including ITGA3, elevate our concern, but to date, the proband's (and sibling's) intellectual and behavioral development have been within normal limits." (PMID 32281310, 2020).
intracerebral haemorrhage (1 paper, 2025). "A recent study showed that the ablation of Col1a1-positive fibroblasts located in the meninges and perivascular space in the CNS exacerbated intracerebral haemorrhage." (PMID 40221393, 2025).
invasive carcinoma (1 paper, 2019). A carcinoma that is not confined to the epithelium, and has spread to the surrounding stroma. "Some of the most significant differential mRNA expressions were found for COL1A1, SPARC, and LGALS1 that were stronger expressed in invasive carcinoma compared to high‐grade dysplasia, and the opposite was shown for S100A7, which was stronger expressed in high‐grade dysplasia." (PMID 31454186, 2019).
ischemia reperfusion injury (1 paper, 2024). Adverse functional, metabolic, or structural changes in ischemic tissues resulting from the restoration of blood flow to the tissue (reperfusion), including swelling; hemorrhage; necrosis; and damage from free radicals. "Both miR-335-3p and miR-338-3p have been shown to protect the myocardium against ischemia-reperfusion injury and prevent fibrosis by inhibiting cell proliferation and migration of cardiac fibroblasts as well as reducing Col1a1 expression." (PMID 38047311, 2024).
Jacobsen syndrome (1 paper, 2022). A multiple congenital anomaly/intellectual disability contiguous gene syndrome caused by partial deletion of the long arm of chromosome 11. "11q24.3–11q25 deletion, most reported as Jacobsen syndrome, and COL1A1 variants were diagnostic in 5 fetuses (0.52%)." (PMID 34980134, 2022).
juvenile idiopathic arthritis (1 paper, 2013). Juvenile idiopathic arthritis (JIA) is the term used to describe a group of inflammatory articular disorders of unknown cause that begin before the age of 16 and last over 6 weeks. "We hypothesize that the polymorphic alleles and genotypes of COL1A1 gene influence bone mineralization and metabolism in children with juvenile idiopathic arthritis (JIA)." (PMID 23763832, 2013).
kidney cancer (1 paper, 2025). Primary or metastatic malignant neoplasm involving the kidney. "COL1A1, a member of the type I collagen family, is associated with tumor cell proliferation and invasion in a variety of cancers, including breast, lung, and kidney cancers." (PMID 40224213, 2025).
lactic acidosis (1 paper, 2023). Metabolic acidosis characterized by the accumulation of lactate in the body. "On the contrary, lactic acidosis increased the expression levels of typical myofibroblast-related genes, such as ACTA2 (i.e., gene encoding α-SMA), COL1A1, and COL1A2, which were 2.5-fold, 3-fold, and 4-fold increased, respectively, compared to the basal conditions." (PMID 36980280, 2023). "Under the same experimental conditions (i.e., lactic acidosis or TGFβ1), the percentages of α-SMA-positive and COL1A1-positive cells/hpf were significantly increased compared to those under basal conditions." (PMID 36980280, 2023). "Briefly, we demonstrated that acADSCs grown under lactic acidosis conditions lose the adipocyte differentiation markers FABP4, C/EBPα, adiponectin, and perilipin-1 while acquiring the myofibroblast markers α-SMA, COL1A1, and COL1A2." (PMID 36980280, 2023).
language disorder (1 paper, 2024). A category of disorders characterized by an impairment in the development of an individual's language capabilities, which is in contrast to his/her non-verbal intellect. "Expressive language disorder/delay was significantly associated with COL1A1/1A2 grouping, with a prevalence of 15% and 0.4% in non-COL1A1/1A2 and COL1A1/1A2 patients, respectively (p < 0.001)." (PMID 39450342, 2024).